TNF (tumor necrosis factor)
Diseases named in the same sentence as TNF in open-access papers (continued):
Sharing a sentence is not in itself a finding about the gene and the disease.
Cerebral ischemia (continued). "Tumor necrosis factor-α (TNF-α) is one of the key immunomodulatory and proinflammatory cytokines upregulated during brain ischemia." (PMID 24285977, 2013). "Accordingly, some have demonstrated that increased TNF-α has a deleterious effect in the acute phases of cerebral ischemia and that TWEAK-induced cell death is mediated by the interaction between TNF-α and TNF receptor 1 (TNFR1)." (PMID 22394384, 2012). "Accordingly, TNFα, IL-6 and IL-1β have been shown to correlate to the severity of SAH, cerebral vasospasm, development of late cerebral ischemia and secondary brain damage in primate." (PMID 23259581, 2012). "Blocking TNF-α by antibodies, TNF binding protein or genetic knockout protects against cerebral ischemia." (PMID 22348126, 2012). "In a diabetic rat model of cerebral ischemia–reperfusion, administration of Res at a dose of 20 mg/kg effectively reduced levels of malondialdehyde (MDA), TNF-α, IL-6 and myeloperoxidase (MPO), while increasing levels of catalase (CAT), superoxide dismutase (SOD), and IL-10." (PMID 41601537, 2026). "Astrocytes during cerebral ischemia mainly activate NF‐κB, signal transducers, and the STAT3 pathway to induce inflammatory cytokines (IL‐6, IL‐1α, IL‐1β, TNF‐α, and interferon‐γ, among others) and release neurotoxic mediators (including NO and ROS), leading to neuronal damage and death." (PMID 41395456, 2025). "Moreover, after reversible experimental local cerebral ischemia, lncRNA H19 was shown to promote leukocyte activation via the miRNA-29b/C1QTNF6 axis, triggering the release of TNF-α and IL-1β, which enhanced neuroinflammation." (PMID 41245147, 2025). "Pro-inflammatory microglia, by secreting cytokines such as interleukin-1β (IL-1β), interleukin-6 (IL-6), tumor necrosis factor-α (TNF-α), inducible nitric oxide synthase (iNOS), and Fc gamma RII/RIII (CD16/32), induce further inflammation and accelerate the pathological course of cerebral ischemia." (PMID 37908731, 2023). "Research shows that the administration of LXA4 methyl ester (LXA4ME) reduces the amount of pro-inflammatory cytokines, tumor necrosis factor-α (TNF-α), interleukin-1β (Il-1β), and increases anti-inflammatory cytokines: IL-10 and transforming growth factor-β1 (TGF-β1) after cerebral ischemia." (PMID 33921615, 2021). "Poldip2 downregulation in RBMECs significantly decreased TNF-induced THP-1 adherence, suggesting that Poldip2 in endothelial cells may play a role in regulating leukocyte adhesion during cerebral ischemia." (PMID 33692398, 2021). "Our results showed that Tanshinone IIA could inhibit the expression of pro-inflammatory factors TNF-α, IL-6, and IL-1β and regulate the levels of SOD and MDA in the brain tissue of rats with cerebral ischemia." (PMID 33953677, 2021). "The results indicated that the inflammatory cytokines TNF‐α, TGF‐β, IL‐6, and IL‐1β were involved in the pathological injury process of cerebral ischemia, whereas casticin could significantly reduce their expression and the damage to brain cells." (PMID 33704926, 2021). "In addition, based on the findings, CNCbl is beneficial to reduce TNF-α production and inhibit lipid peroxidation, also significantly increase anti-oxidant enzyme (GSH and SOD) levels after brain ischemia." (PMID 33953854, 2021). "The results showed that BZP improved focal cerebral ischemia-reperfusion injury in rats and PC12 cells treated with Na2S2O4 in dose/concentration-dependent manners through inhibition of production of 15-HETE and expression of NF-κB, IL-6, TNF-α, and ICAM-1." (PMID 32153408, 2020). "Patients affected by cerebral ischemia, compared to the control group, had an increased quantity of cytokines and adhesion molecules in plasma, such as E-selectin, P- selectin, V-CAM-1, ICAM-1, IL-1, IL-6, and TNF-α." (PMID 32899616, 2020). "Upregulation of IL-17 mRNA can induce the expression of IL-1, IL-6, IL-8, TNF-α, and ICAM-1, which may aggravate the secondary inflammatory reaction after cerebral ischemia." (PMID 32194375, 2020).
Cerebral ischemia (continued). "Previous studies have demonstrated that Andro could decrease the production of cytokines including TNF-α and IL-1β, and pro-inflammatory factors such as PGE2 through inhibiting NF-κB activation to protect against cerebral ischemia." (PMID 30294256, 2018). "Furthermore, curcumin (200 mg/kg) attenuates inflammation by decreasing inflammatory mediators, such as interleukin-1 beta (IL-1β), tumor necrosis factor-alpha (TNF-α), Prostaglandin E2 (PGE2), NO, COX-2, and iNOS, induced by brain ischemia in rats." (PMID 29220411, 2017). "Absence of TNF – alpha expression has been to enhance neuronal death when cerebral ischemia was induced in mice models." (PMID 27875990, 2016). "However, interleukin-6 (IL-6) and tumor necrosis factor-α (TNF-α), two inflammatory cytokines that are accumulated during cerebral ischemia, play a protective role in the incidence of HIE." (PMID 25187835, 2014). "In contrast in mice lacking the TNFR1 neuronal damage after focal cerebral ischemia-reperfusion was significantly increased suggesting a neuroprotective role of TNFα after acute brain insults." (PMID 24964076, 2014). "Mice lacking TLR4 receiving pre-conditioning prior to permanent cerebral ischemia are not protected and show reduced NF-κB activation and lower expression levels of TNF-α compared to wild-type animals." (PMID 25239168, 2014). "The aim of the present study was to determine whether TNF-α regulates the expression level of EAAT2 in primary astrocytes in culture and its role in brain ischemia." (PMID 25371754, 2014). "The aim of the present study was to determine whether tumor necrosis factor (TNF)-α regulates the expression levels of excitatory amino-acid transporters (EAATs) in primary astrocytes and its roles in brain ischemia." (PMID 25371754, 2014). "Experimentally and clinically, proinflammatory mediators, such as tumor necrosis factor (TNF)-α, are rapidly released from injured tissue in the acute phase of cerebral ischemia; this induces the recruitment and activation of inflammatory cells, including various types of leukocytes." (PMID 23972823, 2013). "In addition, curcumin suppressed neuroinflammatory response by decreasing inflammatory mediators, such as IL-1β, TNF-α, PGE2, NO, COX-2, and iNOS induced by cerebral ischemia of rats." (PMID 23762140, 2013). "It is notable that cerebral ischemia did not change the levels of plasma proinflammatory cytokines TNF-α and IL-1β, but significantly increased the levels of plasma IL-6 and C-reactive protein, which were attenuated by propofol treatment." (PMID 24349350, 2013). "Results showed that sevoflurane postconditioning can decrease serum tumor necrosis factor-alpha (TNF-α), interleukin-1 beta (IL-1β), nitric oxide (NO), nitric oxide synthase (NOS) and increase serum interleukin-10 (IL-10) levels in cerebral ischemia reperfusion rats." (PMID 22210172, 2011). "TNFα, IL-1β, IL-6 and MCP-1 expression was substantially upregulated after brain ischemia." (PMID 22196138, 2011). "We induced focal cerebral ischemia by unilateral MCA suture-occlusion in TNFα-Tg rats and non-Tg littermates." (PMID 18947406, 2008). "In the context of cerebral ischemia, TIGAR has been shown to exert neuroprotective effects by reducing oxidative stress, supporting mitochondrial function, and mediating downregulation of pro-inflammatory markers such as iNOS, COX-2, IL-1β, and TNF-α in astrocytes." (PMID 41342963, 2025). "Indeed, CCR2 knockout mice, which are largely deficient in classical monocytes in the periphery, show decreased levels of IL-1β and Tumor Necrosis Factor (TNF)-α and an increase in the anti-inflammatory cytokines IL-4, IL-5 and IL-13 at the site of inflammation during cerebral ischemia." (PMID 34804052, 2021).
Cerebral ischemia (continued). "In models of cerebral ischemia and neuronal cultures, EGCG promotes neuronal protection regulated by the Nrf2/HO-1 pathway by attenuating both ROS production and nuclear factor κB (NF-κB) activation, which consequently suppresses the expression of TNFα, IL-1β, IL-6, and iNOS." (PMID 32466215, 2020). "CpG preconditioning significantly increased the level of TNF-α in the serum of mice prior to MCAO, and TNF-α was essential to the subsequent protective effect of the brain because CpG preconditioning in TNF-α-knockout mice did not produce the protective effect against cerebral ischemia." (PMID 25928750, 2015). "Poly-IC treatment reduced the levels of TNF-α and IL-1β in the ischemic brain tissue, cerebrospinal fluid, and peripheral blood and increased IFN-β levels, suggesting that poly-IC plays an important role in the protection of cerebral ischemia by reducing the inflammatory processes." (PMID 25928750, 2015). "However, in the same study, both intravenous and intraperitoneal routes of TNF-α administration failed to exert neuroprotection against cerebral ischemia." (PMID 24624056, 2014). "IL-6, glutamate and TNF-α levels were not higher in cerebral ischemia than in controls." (PMID 25086655, 2014). "IL-6, Glutamate and TNF-α are not specific for cerebral ischemia either in humans or in rats." (PMID 25086655, 2014). "Furthermore, we showed that eNAMPT triggered the release of TNF-α, whereas TNF-α neutralizing antibody attenuated NAMPT-enhanced neuronal injury after OGD and reperfusion, thus implicating TNF-α in the injurious process of eNAMPT on cerebral ischemia." (PMID 24392007, 2013). "Thus, eNAMPT is an injurious and inflammatory factor in cerebral ischemia and aggravates ischemic neuronal injury by triggering TNF-α release from glia cells, via a mechanism not related to NAMPT enzymatic activity." (PMID 24392007, 2013). "In the present study, we, therefore, investigate the hypothesis that RA plays a neuroprotective role through the abrogation of HMGB1 release and NF-κB activation triggered by tumor necrosis factor-α (TNF-α) and ameliorates diabetic rats with MCAO-induced cerebral ischemia/reperfusion injury." (PMID 23414442, 2013). "Moreover, Tat-NTS—a related peptide—protects against cerebral ischemia/reperfusion injury by enhancing SUMOylation of ANXA1, thereby promoting NBR1-dependent selective autophagic degradation of IKKα, suppressing NF-κB activation, and reducing IL-1β and TNF-α release in microglia." (PMID 41007413, 2025). "In addition, animal studies demonstrated that the cerebral infarction volume and the degree of brain damage after cerebral ischemia in mice lacking the TNF receptor gene are significantly higher than those in wild-type mice, suggesting the neuroprotective role of TNF." (PMID 35097126, 2022). "By replicating the rat model of cerebral ischemia, this study explored whether THSWD can reduce cell necrosis and neuroinflammation in the rat model of MCAO by inhibiting the expression levels of MCP-1, IL-1β, IBA-1, and MPO inflammatory factors as well as the TNF-α/RIP1/RIP3/MLKL pathway." (PMID 34447315, 2021). "Similarly, IL-6, Glu and TNF-α are non-specific to cerebral ischemia in biomarker studies in rats." (PMID 25086655, 2014). "The co-administration of PDRN and DMPX failed to decrease TNF-α and IL-1β expressions observed with PDRN in cerebral ischemia." (PMID 33735236, 2021). "The productions of IL-1β, TNF-α, PGE2, and NO significantly increased in rat cortex with cerebral ischemia." (PMID 23762140, 2013). "Indeed, the present study showed that PC(16:0/16:0) suppressed LPS-evoked microglial production of IL-1β and TNF-α, while LPC(16:0) did not, indicating that cerebral ischemia tipped the balance of PC-LPC ratio, which is regulated by the Lands cycle." (PMID 33288676, 2021).
Cerebral ischemia (continued). "We anticipated that TNFα-Tg rats would have relatively smaller numbers of surviving neurons in ischemic cortex and/or in the CA1 region of ipsilateral hippocampus, when examined 28 days after focal cerebral ischemia as compared to non-Tg littermates." (PMID 27144978, 2016).
hepatocellular carcinoma (404 papers, 2003 to 2026). A malignant tumor that arises from hepatocytes. "More recently, in metabolic dysfunction-associated steatohepatitis-driven hepatocellular carcinoma has been shown the efficacy of a tumor necrosis factor-alpha TNF-α inhibitor (Marimastat), a Che-1 antagonist." (PMID 39695699, 2024). "In the current study, we report that the pro-inflammatory mediator TNF-α causes shedding of membrane-bound LDL-R from human hepatoma (HepG2) cells through increased activity of peptidases ADAM-17 and MMP-14." (PMID 37861809, 2023). "Previous studies have reported that TNF-α is positively associated with high-grade tumors and predicts poor survival in patients with hepatocellular carcinoma." (PMID 36559076, 2022). "In early studies, TNFα was noted to have an impact on protein degradation rates in cardiac muscle after observing a decrease in protein loss in hepatoma mice receiving anti-TNF treatment." (PMID 35326491, 2022). "Here, accompanying lipidomic data determine the PC structural variants that have been identified in human hepatoma HepG2 cells and those whose relative abundance is modified by TNFα." (PMID 31667320, 2019). "Our result also indicated that the TNF-α T-857C polymorphism also plays an important role in hepatocellular cancer development." (PMID 28115787, 2016). "In the stratified analysis based on HWE, we found an elevated risk between the TNF-α T-857C polymorphism and hepatocellular cancer susceptibility." (PMID 28115787, 2016). "An increased risk between the TNF-α T-857C polymorphism and hepatocellular cancer susceptibility in homozygote genetic model and recessive genetic model was also found." (PMID 28115787, 2016). "Our analysis provided some evidence to support an elevated risk between the TNF-α T-857C polymorphism and gastric cancer and hepatocellular cancer susceptibility." (PMID 28115787, 2016). "They demonstrated that overexpression of ephrinA2 in hepatocellular carcinoma cells leads to enhanced tumor cell survival and proved that this is caused by resistance to tumor necrosis factor-α-(TNF-α-) induced apoptosis." (PMID 20224755, 2010). "Mainly, cyanidin‐3‐O‐glucoside suppresses inflammation and the production of pro‐inflammatory cytokines (COX‐2, TNF‐α, and IL‐6) in colorectal and hepatocellular carcinoma and causes cell cycle inhibition and mitochondrial dysfunction in ovarian and cervical malignancies." (PMID 40321606, 2025). "It upregulates the production of pro-inflammatory cytokines, including tumor necrosis factor-α (TNF-α) and interleukins (IL-1β, IL-6), thereby triggering hepatic fibrosis and necro-inflammatory responses, which ultimately increase the risk of hepatocellular carcinoma." (PMID 41294896, 2025). "Similarly, irradiation of hepatoma cells has been linked to the secretion of tumor necrosis factor-alpha (TNF-α), IL-6, VEGF, epidermal growth factor (EGF), MMP2, and MMP9, all of which enhance tumor invasion." (PMID 39759518, 2024). "Additionally, adipokines, resistin, leptin, visfatin, and tumor necrosis factor α (TNF-α) are proteins secreted by visceral adipose tissues that can affect how the liver functions and cause inflammation, cirrhosis, and hepatocellular cancer." (PMID 37374119, 2023). "In addition, previous studies have demonstrated that the increased expression of TNF-α is associated with poor survival in endometrial, colorectal, and hepatocellular cancers." (PMID 36765695, 2023). "In another study, in hepatocellular carcinoma, treating MSCs with tumor necrosis factor-α (TNF-α) and interferon γ (IFNγ) causes an increase in production of TGFβ by MSCs which in turn could promote tumor metastasis by inducing EMT in cancer cells." (PMID 35251985, 2022). "Treatment with DENA/2-AAF also increased TNF-α, a reliable marker of inflammation in hepatic carcinoma, while isatin cotreatment significantly reduced hepatic TNF-α, confirming an anti-inflammatory effect associated with protection against hepatocarcinogenesis." (PMID 35453384, 2022).
hepatocellular carcinoma (continued). "The testing method was the polymerase chain reaction-restriction fragment length polymorphism (PCR-RFLP), which was used in 8 of those 11 studies they reported that the TNF α -238 G>A polymorphism was significantly associated with increased risk of hepatocellular carcinoma." (PMID 33773554, 2021). "For instance, TNF-α -308 polymorphism is significantly associated with the risk of gastric and hepatocellular carcinomas, triple-negative breast cancer, myeloma, and lymphoma, suggesting that TNF-α may be conducive to the early diagnosis of malignancies." (PMID 28575042, 2017). "Our meta-analyses suggest that TNF-α T-857C polymorphism may be associated with increased risk of gastric cancer and hepatocellular cancer development." (PMID 28115787, 2016). "In the subsequent in vitro studies, IL-19 raised the level of TNF-α and IL-10 transcripts in hepatoma cells, which may cause liver inflammation and lead to hepatic damage." (PMID 23468852, 2013). "In addition to these results, two meta-analyses evaluating the association of polymorphisms of TNF-α and hepatocellular carcinoma risk also revealed similar results." (PMID 27785252, 2013). "Moreover, It has been mentioned that the release of various proteins from visceral adipose tissues, including adipokines, resistin, leptin, visfatin, and tumor necrosis factor α, can impact liver function, potentially causing inflammation, cirrhosis, and hepatocellular cancer." (PMID 38179344, 2023). "The TNF-α rs 1800629 minor A allele was a risk factor to develop liver cirrhosis and hepatocellular carcinoma following HBV infection in a Han Chinese population, suggesting that the protective or deleterious roles of TNF-α expression may vary depending on the infecting virus." (PMID 31574965, 2019). "Therefore, the TNF-α T-857C polymorphism could be considered as one possible risk factor of gastric cancer and hepatocellular cancer according to our study." (PMID 28115787, 2016). "The aim of the present study was to evaluate the influence of tumor necrosis factor-alpha (TNF-α) −308 G > A polymorphism on hepatocellular carcinoma (HCC) risk." (PMID 25420786, 2014). "Functional assays demonstrated that DHA-treated cells exhibited increased secretion of TNF, IL1β, ROS, and PD-L1, accompanied by enhanced cytotoxic activity against hepatocellular carcinoma cells in a co-culture system." (PMID 41599687, 2026). "Furthermore, the study indicates that the combined elevation of TNF-α and IL-6 levels increases the risk of hepatocellular carcinoma (HCC)." (PMID 40806358, 2025). "Studies have shown that in hepatocellular carcinoma, down-regulation of UCK2 induces cell cycle arrest and activates the age-related secretory phenotype associated with the TNF-α NFκB signaling pathway to alter the tumor microenvironment." (PMID 39931080, 2025). "These alterations were correlated with a decrease in inflammatory cytokines (MCP-1, TNF-α), suggesting a potential suppression of NASH-associated hepatocellular carcinoma." (PMID 41257640, 2025). "Melatonin demonstrates oncostatic efficacy in hepatocellular carcinoma (HCC) through dual-pathway modulation: suppressing NF-κB transcriptional activation while attenuating TNF-α-mediated proinflammatory cascades." (PMID 40756978, 2025). "For instance, in a rat hepatoma model, liposomal IL-2 significantly increased survival time compared to free IL-2 or saline, largely due to enhanced macrophage activation and tumor necrosis factor alpha (TNF-α) production." (PMID 40143046, 2025). "In the liver, TNF-α is known to induce the apoptosis and necroptosis of hepatocytes, hepatitis, autoimmunity, and progression to hepatocellular carcinoma." (PMID 40283142, 2025). "Previous studies observed a cytokine-mediated upregulation of CD55 and CD59 expression in human hepatoma cells in tumors mediated via pro-inflammatory cytokines such as tumor necrosis factor-alpha, IL-1 beta, and IL-6." (PMID 40723265, 2025).